CRP (C-reactive protein)
Diseases named in the same sentence as CRP in open-access papers (continued):
Sharing a sentence is not in itself a finding about the gene and the disease.
bacterial infection (continued). "Therefore, neither CRP nor PCT seems to be able to discriminate between viral triggered HLH and severe bacterial infection." (PMID 29411124, 2018). "In our study, the accuracy of PCT measured on the day of fever onset was significantly higher, with an AUC value of 0.715, than that of other inflammatory markers such as CRP (AUC 0.598) and WBC counts (AUC 0.502) to discriminate fever related to bacterial infection from noninfectious fever." (PMID 29849829, 2018). "Research results demonstrated that, the serum PCT, CRP and WBC levels of the bacterial infection group and the non-bacterial infection group were remarkably higher than those of the control group and moreover the levels of the bacterial infection group were the highest." (PMID 28083019, 2016). "Serum PCT measurement relies on a quick and routine lab test that has been reported to accurately differentiate between systemic bacterial infection and non-infectious acute inflammatory states, whereas white blood cells count (WBC) and serum C-reactive protein (CRP) failed to do so." (PMID 18366777, 2008). "One hundred-twenty six patients were studied and it was reported that leukocyte count, CRP and lactate levels were higher in blood culture positive patients but the difference was not significant despite finding that PCT had higher negative predictive value in ruling out bacterial infection." (PMID 36167572, 2022). "We hypothesise that this response is particularly pronounced if there is a mismatch between the internal biomedical logic of the CRP POCT and patients’ own “explanatory models” – which at least until recently did not commonly incorporate notions of bacterial infection (Sringernyuang, 2000, 133–135)." (PMID 29499522, 2018). "Although this solution would require clinical validation of the CRP POCT for a wider range of health conditions, it could potentially avoid a mismatch with local expectations for primary-care-level antibiotic treatment in the absence of bacterial infections, for example, for muscle pains." (PMID 29633689, 2018).
infectious disease (326 papers, 2004 to 2026). A disorder directly resulting from the presence and activity of a microbial, viral, or parasitic agent in humans. "The utility of CRP as a diagnostic and prognostic biomarker is well recognized in a broad range of infectious diseases." (PMID 41010302, 2025). "Numerous studies have shown that specific blood parameters, such as C-reactive protein, procalcitonin and neutrophil to lymphocyte ratio, provide significant diagnostic and prognostic value for infectious diseases." (PMID 39652607, 2024). "Low-grade systemic inflammation measured as high sensitivity C-reactive protein (hs-CRP) has been associated with non-communicable disease risk." (PMID 38225452, 2024). "The CRP gene codes for a critical component of the innate immune system and CRP variants have been reported associated with infectious disease and vaccination outcomes." (PMID 38662664, 2024). "The differential patterns observed in arachidonic acid, IL-6, and CRP levels among the infectious disease groups suggest distinct immunological signatures associated with each pathogen." (PMID 39066228, 2024). "Higher WBC counts, CRP levels, and extended hospital stays were associated with the severity of infectious disease." (PMID 37794030, 2023). "In humans, some inflammatory and infectious diseases cause extreme increases in CRP values (>100 mg/L) more frequently than others." (PMID 36865442, 2023). "Although elevated levels of IL-6 and CRP can also be caused by various infectious diseases, our study suggests that PE should also be considered in children with these markers." (PMID 37474910, 2023). "After the organism is infected with different pathogenic bacteria, the CRP concentration increases significantly earlier than leukocyte indicators and is higher than in non-infectious diseases." (PMID 35755831, 2022). "CRP is an acute-phase reactant secreted by hepatocytes and is an important diagnostic test for laboratory screening of infectious and non-infectious diseases." (PMID 35874904, 2022). "Serial CRP level measurement is widely used to monitor the clinical responses of patients with infectious diseases, but few authors have studied the diagnostic value of serial CRP level measurements." (PMID 35626186, 2022). "As a widely used diagnostic indicator for differentiating infectious and non-infectious diseases, (serum) CRP showed high clinical diagnostic value (AUC > 0.87) in differentiating infectious PE (TPE, CPPE, and UPPE) from PE caused by CTDs." (PMID 33740937, 2021). "C-reactive protein (CRP) has been studied extensively for association with a large number of non-infectious diseases and outcomes." (PMID 32978716, 2021). "Various infectious disease cause mucocutaneous rashes in combination with neutrophilia and elevated C-reactive protein (CRP)." (PMID 34350146, 2021). "The lack of interference effects has to be claimed as a major advantage in CRP analysis as associated metabolic states frequently occur in patients with inflammatory and infectious diseases." (PMID 28558755, 2017). "PTX3 is a member of the long pentraxin subfamily while the C-reactive protein (CRP) is the prototype of short pentraxin and has been widely used, with limited diagnostic and prognostic specificity in infectious diseases." (PMID 25097729, 2014). "Conversely, serum CRP has been widely used as a marker for inflammation and tissue injury, as well as for diagnostic purposes, thereby differentiating inflammatory and infectious diseases." (PMID 20512289, 2009). "Studies have shown that mtDNA is associated with CRP expression in infectious disease." (PMID 38241222, 2024). "Additionally, this study contributes valuable support for the use of PTX3 as a diagnostic marker in suspected cases, akin to the way CRP is employed in clinical practice for infectious diseases." (PMID 38053036, 2023). "The value of C-reactive protein (CRP) in infectious diseases has been recognized, but the diagnostic value of CRP in chronic PJI is unknown." (PMID 34372816, 2021).
infectious disease (continued). "As the main reason for tooth loss, oral bacterial infectious diseases are associated with a chronic low-grade inflammation, which can upregulate inflammatory biomarkers including C-reactive protein (CRP), tumor necrosis factor alpha (TNF-alpha), and interleukin-6 (IL-6)." (PMID 32649678, 2020). "For example, while other inflammatory indices such as the neutrophil-to-lymphocyte ratio have been linked to adverse outcomes in infectious diseases, the CRP/albumin ratio may capture a broader pathophysiological profile by integrating markers of inflammation with baseline physiological reserve." (PMID 40872333, 2025). "However, the increasing workload of GPs and the need for adequate diagnostic tests in infectious diseases could be solved by an expansion of CRP-POCTs in the German primary care setting." (PMID 39313318, 2025). "In the blood of healthy individuals C-reactive protein (CRP) is typically quite scarce, whereas its blood concentration can rise robustly and rapidly in response to tissue damage and inflammation associated with trauma and infectious and non-infectious diseases." (PMID 33633738, 2020). "CRP levels can regulate the development of inflammation, promote chronic inflammation, and significantly increase in infectious diseases." (PMID 40832148, 2025). "CRP, an acute‐phase reactant, is elevated in most inflammatory and infectious diseases, including PTB." (PMID 40453733, 2025). "All antibiotics were prescribed in consultation with the division of infectious disease and discontinued once CRP and WBC levels normalized." (PMID 40760640, 2025). "CRP is also commonly utilized to monitor the severity and recurrence of infectious diseases, including COM." (PMID 40595978, 2025). "In many other fields of infectious diseases, the cessation of systemic antibiotic use after the achievement of CRP level normalization has been debated for decades and research regularly denies its practicability or benefit." (PMID 40565868, 2025). "The findings indicate that elevated NPAR is more prevalent among RA patients who smoke, exhibit high levels of CRP and neutrophils, have OP, infectious diseases, and are of advanced age (P<0.001, P<0.05)." (PMID 41041308, 2025). "The immune-modulatory effects of microbial metabolites also extend to infectious diseases, which influence vital markers such as cytokines, C-reactive protein (CRP), and tumor necrosis factor-alpha (TNF-α)." (PMID 39857684, 2025). "Concurrently, C-reactive protein (CRP), recognized as a core mediator of systemic inflammation, has expanded its clinical significance beyond a marker for infectious diseases." (PMID 41347140, 2025). "A comprehensive infectious disease work-up, including complete blood count, C-reactive protein, erythrocyte sedimentation rate, and microbial culture, was not available due to logistical constraints in real-world practice." (PMID 39797265, 2024). "In studies investigating infectious diseases in pigs, haptoglobin has a longer period of elevation compared to other acute-phase inflammatory proteins, including CRP and pig-MAP." (PMID 38791689, 2024). "CRP is known as a marker of inflammation, either acute due to infectious disease or chronic due to other disease states, such as atherosclerotic cardiovascular disease, both of which can impact physical function." (PMID 39081837, 2024). "Conversely, CRP’s significant rise during acute inflammation has made it a longstanding marker for inflammatory or infectious diseases, particularly in pediatric cases." (PMID 39768616, 2024). "This meta-analysis showed that in non-infectious diseases, the expression of plasma mtDNA is correlated with the expression of CRP." (PMID 38241222, 2024). "Concerning laboratory blood tests, CRP values had returned to normal ranges in 84% (n = 188) of the patients, proving recovery from the infectious disease." (PMID 37103058, 2023).
infectious disease (continued). "Neurosurgery and Infectious Disease specialists monitored him with serial C-reactive protein (CRP) measurements." (PMID 38036498, 2023). "Future large-scale studies are needed to confirm our results and apply this method to daily clinical work to improve the performance of CRP in predicting infectious diseases in maintenance hemodialysis patients." (PMID 37016028, 2023). "For Jomon hunter-gatherers, increased triglyceride and blood sugar levels were important for resistance to starvation, whereas for continental East Asian farmers, increased CRP and eosinophil counts were important for protection against infectious diseases." (PMID 36879818, 2023). "In contrast, CRP is a clinically well-characterized inflammatory marker widely measured in the diagnosis of infectious diseases." (PMID 37176638, 2023). "For example, the C-reactive protein (CRP) level in the serum typically falls below 1 mg/L in healthy adults; however, the CRP level rapidly rises in the majority of infectious diseases." (PMID 37640734, 2023). "CRP is one of the most sensitive indicators of inflammatory response for diagnosing infectious diseases, and its elevated levels suggest that the body is in an inflammatory or oxidative stress state." (PMID 37550622, 2023). "Some researchers believe that simultaneous detection of IL-6, CRP and procalcitonin can improve the detection rate of early inflammation in the event of inflammation or infectious diseases." (PMID 37442959, 2023). "Studies have shown that women had very high C-reactive protein and neutrophil levels and erythrocyte sedimentation rate in infectious diseases." (PMID 37580672, 2023). "A retrospective study of FUO population also revealed a higher median level of CRP in connective tissue diseases than in infectious diseases." (PMID 36482449, 2022). "Human CRP transgenic mice have been demonstrated to be a good model for studying the in vivo function of the protein and have been used to study infectious diseases." (PMID 36275680, 2022). "After treatment, none of the six patients displayed any signs of NEC or other infectious diseases, based on clinical presentation and radiological examination, and their serum CRP levels were found to be dramatically decreased." (PMID 36188574, 2022). "Studies report the usefulness of suPAR in predicting severe outcomes in critical illness related to inflammatory and infectious diseases, along with CRP and leukocytes." (PMID 36579490, 2022). "Since HMGB1 was found to be elevated in inflammatory and infectious diseases as well, we recorded corresponding CRP levels (n = 61) and data on infections (n = 53) and treatment-associated toxicity (n = 58) during therapy." (PMID 34671818, 2022). "C-reactive protein-to-albumin ratio (CAR) is an independent risk factor in cardiovascular, cerebrovascular, and infectious diseases." (PMID 36006278, 2022). "Her lab findings were remarkable for elevated erythrocyte sedimentation rate (ESR) and C-reactive protein (CRP) and unremarkable for a broad infectious disease workup." (PMID 35273868, 2022). "Particularly, work-up for infectious diseases was frequently done in patients with fever and a high CRP." (PMID 35237621, 2022). "CRP is one of the most widely used inflammatory markers in the identification of infectious diseases, which is synthesized primarily in liver hepatocytes but also by smooth muscle cells, macrophages, endothelial cells, lymphocytes, and adipocytes." (PMID 34372816, 2021). "C-reactive protein (CRP) was first recognized in the 1940s as a protein that appeared in blood during acute episodes of infectious disease." (PMID 34552600, 2021). "C-reactive protein, which is a widely used inflammatory marker for patients with infectious diseases, was more predictive of ARDS in this study than other laboratory values, which is consistent with a previous study." (PMID 33897912, 2021).
infectious disease (continued). "Procalcitonin, CRP and sedimentation rate are all inflammatory markers which are expected to increase in infectious diseases." (PMID 33614298, 2021). "Elevated CRP levels were detected in 41.7% of patients with infectious diseases, followed by circulatory (35.0%), genitourinary (34.8%), digestive (20.0%), and respiratory diseases (18.8%), and diseases of the nervous system (28.6%)." (PMID 34830693, 2021). "C-reactive protein (CRP) has long been the key marker of inflammatory, thrombotic and infectious diseases, although showing suboptimal specificity." (PMID 33413127, 2021). "Measurement of acute phase proteins, such as C-reactive protein, is routinely used for diagnosis and determining the prognosis of infectious disease." (PMID 33315349, 2021). "A specific correlation between SAA proteins and CRP has been found in several infectious diseases with the concentration of SAA increasing up to 2,000 mg/l." (PMID 34168074, 2021). "The ratio of SAA to CRP, for example, has been proposed as an indicator of infectious disease severity in children." (PMID 32253915, 2020). "As will be detailed later, these varied ligand and receptor interactions also support CRP’s participation in various non-infectious diseases." (PMID 33633738, 2020). "In our case, WBC, ESR, and CRP were sufficiently elevated to suggest the possibility of spinal infectious disease." (PMID 32011480, 2020). "Combined values of NLR or PLR and CRP have been studied as a more reliable marker to predict prognosis or evaluate the severity of malignant or infectious diseases." (PMID 31402523, 2019). "Changes in the plasma concentrations of the CRP, which is considered a marker of inflammation, are commonly reported in people with infectious diseases, especially during an inflammatory response." (PMID 31877169, 2019). "The group of patients with a final diagnosis of non-communicable disease had very low concentrations of CRP and PCT." (PMID 31664120, 2019). "White blood cells WBCs and CRP have been widely adopted to trace down infections in internal medicine and to follow the course of infectious diseases." (PMID 29866067, 2018). "The present study provides insight into the disadvantage of over-reliance on CRP levels in prescribing antibiotics in cases of enteroviral infectious diseases among pediatricians." (PMID 30192893, 2018). "Many of the patients hospitalized in internal medicine wards have inflammatory or infectious diseases and elevated markers of tissue injury such as CRP." (PMID 30373567, 2018). "In dogs, an increase of CRP was shown in several conditions including infectious diseases, immune mediated diseases, neoplasias, and surgery." (PMID 28558755, 2017). "Patients with infectious diseases had significantly higher levels of CRP than patients with active AAV." (PMID 28962592, 2017). "Recently, the CRP/albumin (CRP/Alb) ratio was recognized as a novel inflammatory index in infectious disease." (PMID 28676731, 2017). "The white blood cell count (WBC), neutrophil count, lymphocyte count and C-reactive protein (CRP) levels are among the most commonly used hematological parameters for monitoring the effectiveness of infectious disease treatment." (PMID 27068888, 2016). "C-reactive protein is a major acute phase protein and a sensitive marker of inflammation in dogs and has been used as a biomarker of infectious diseases." (PMID 27623952, 2016). "Statistically, these cutoff values are useful for prediction of toxic voriconazole level, although the value of 4.7 of CRP is less clinically important, since the value is common level of infectious diseases." (PMID 27096102, 2016). "Plasma CRP levels are time-dependent,which increased rapidly within 4–6 h, and reached peak values at 36–50 h, in acute inflammation, trauma or infectious diseases, and then decreased as the inflammation response was attenuated." (PMID 26555752, 2015).